IL11 (interleukin 11)
Diseases named in the same sentence as IL11 in open-access papers (continued):
Sharing a sentence is not in itself a finding about the gene and the disease.
tumor (continued). "IL11 may trigger tumor cells to release IL33, potentially shifting it from an alarmin to an actively secreted product." (PMID 34235145, 2021). "To determine whether MAFF-induced IL11 affects tumor cell invasion through STAT3 signaling, we first measured phospho-STAT3 protein levels." (PMID 34262028, 2021). "However, compared to shSCR group, MAFF knockdown MDA-MB-231 tumors with IL11 overexpression displayed similar levels of tumor metastasis as shSCR controls, mirroring the rescue effects from our in vitro studies." (PMID 34262028, 2021). "As inflammation progresses, it promotes the production of tumor-promoting cytokines such as IL-11, IL-1β, and IL-6, which support the survival, growth, and metastasis of tumor cells." (PMID 34150765, 2021). "These tumor organoids were transplanted into the colons of Il11-Egfp reporter mice, and we examined whether IL-11+ fibroblasts appeared along with tumor development." (PMID 33863879, 2021). "Since many of the genes enriched in IL-11+ fibroblasts were also upregulated in tumor tissues, we hypothesized that the genes with elevated expression in IL-11+ fibroblasts might critically affect the prognosis of cancer patients." (PMID 33863879, 2021). "Thus, IL-11+ fibroblasts produce several growth factors that induce the proliferation of nearby tumor cells." (PMID 33863879, 2021). "Given that IL11FS and IL11RS might be different, IL-11 activates both fibroblasts and tumor cells, thereby contributing to CRC progression." (PMID 33863879, 2021). "The key downstream activator of crosstalk between CAFs and the tumour epithelial cells is interleukin 11 (IL-11), upregulated in the CAFs by tumour-derived TGFβ, a key cytokine-dependent mechanism that promotes a prometastatic phenotype in tumour epithelial cells." (PMID 33669775, 2021). "This feed-forward loop between fibroblasts and tumor cells via secreted IL-11 from IL-11+ fibroblasts might contribute to tumor progression." (PMID 33863879, 2021). "YTHDF2 can also inhibit HCC tumor cells and related vessels by processing IL11 and SERPINE2 mRNAs." (PMID 34105069, 2021). "In addition, exogenously expressed IL11 rescued the decreased invasion in MAFF knockdown cells, suggesting that MAFF regulates tumor cell invasion through the IL11 pathway." (PMID 34262028, 2021). "Hence, these data point out for the first time the role of IL11 produced by BC cells in stimulating the aggressive features of the tumor microenvironment components such as CAFs." (PMID 34841688, 2021). "Tumour cells can secrete platelet agonists to induce platelet aggregation, which results in thrombocytosis by producing thrombopoietic cytokines such as interleukin (IL)-1, IL-3, IL-11, and particularly tumour-derived IL-6." (PMID 32312252, 2020). "Tumorigenic cytokines such as IL-6 and IL-11 could directly act on tumor cells, enhancing cell proliferation, stimulating angiogenesis, and expanding cancer stem cell (CSC) population, in mouse xenograft models of gastrointestinal and breast cancers." (PMID 33363537, 2020). "To confirm the effect of IL‐11 in vivo, we further measured the xenograft tumor growth." (PMID 31273847, 2019). "We then hypothesized that bazedoxifene treatment of tumor‐bearing mice would induce the same signaling “hallmarks” observed upon treatment of gp130Y757F mice with either IL11‐Mutein or JAK inhibitors." (PMID 30885958, 2019). "Our results did not exclude the possibility that MTERFD1 might induce IL-6 and IL-11 production in these tumor stromal cells and infiltrated immune cells to promote CRC development in a paracrine manner; this possibility requires further investigation." (PMID 31754344, 2019). "It is known that malignant epithelial cells secrete antiadipogenic cytokines, such as TNF-α, IL-11, and IL-6 that inhibit the differentiation of fibroblasts near the tumor into mature adipocytes and stimulate aromatase expression in these undifferentiated adipose fibroblasts." (PMID 31412584, 2019).
tumor (continued). "Moreover, IL-11 was 4.88-fold higher in GBC tissues than corresponding non-tumor tissues from GSE76633." (PMID 30086773, 2018). "In addition, lncRNA-ATB promotes organ colonization of disseminated tumor cells by binding to interleukin-11 mRNA and triggering the STAT3 signaling pathway." (PMID 29108251, 2017). "Administration of recombinant human IL11 to mice (n = 4/group) activated IL11 downstream target, signal transducers and activators of transcription (STAT3) and significantly increased tumour growth (p < 0.05), suggesting that IL11 promotes high grade tumour growth." (PMID 28186993, 2017). "Considering the important role of IL-11/STAT3 signaling pathway in tumor progression and metastasis, therapeutic options using direct STAT3 inhibitors or upstream inhibitors might be used for the treatment of ccRCC in the future." (PMID 29100303, 2017). "Endogenous IL11 protein was also detectable in AN3CA tumour lystaes (976.6 pg/ml ± 61.3)." (PMID 28186993, 2017). "The results validated that IL-11 secreted from CAF could significantly attenuate the anti-tumor effect of cisplatin." (PMID 27922075, 2016). "The correlation between IL-11 and chemoresistance of tumor cells has also aroused our interests." (PMID 27922075, 2016). "Interestingly we were able to quantify the expression in tumor bearing mice of the human chemokines IL-11 and CCL20, known as key players in the regulation of cancer cell migration and progression from different solid tumors." (PMID 27322553, 2016). "The results validated that IL-11 secreted from fibroblasts could also attenuate the anti-tumor effect of cisplatin in immune-competent mice." (PMID 27922075, 2016). "MiR-204-5p has believed to be a tumor suppressor and can attenuate IL-11 expression." (PMID 27028859, 2016). "The role of IL-1RT1 signaling during IL-11-induced STAT3 activation without tumor inducing gp130 mutations was also assessed." (PMID 25528766, 2015). "In fact, in the absence of IL-1RT1 signaling gastric pathology develops more rapidly and extensively in both the antrum and gastric cardia suggesting that IL-1RT1 signaling may minimize tumor burden by antagonizing IL-11/STAT3 mediated pathology." (PMID 25528766, 2015). "Our present data suggest that IL-11-induced MDSCs may play a role in the immunosuppression of tumour microenvironments." (PMID 28781374, 2015). "IL-11 expression depends on the canonical pathway in tumor cells, but also involves MAPK pathways." (PMID 25197981, 2014). "Quantitative RT-PCR analysis showed a significant increase in expression of IL-6 and IL-11 mRNA expression in tumour xenografts in SP-treated animals compared to the control group (2.7±0.2 fold, P<0.01 and 2.6±0.1 fold, P<0.05 for SP vs control for IL-6 and IL-11, respectively)." (PMID 22442729, 2012). "Very little immunoreactive IL11 and IL11Rα was seen in the stromal compartment of the tumours." (PMID 20553623, 2010). "IL11 staining was also present in vascular endothelial and smooth muscle cells in Grade 3 tumours." (PMID 20553623, 2010). "TGF-β has an additional role in cancer to promote bone metastasis by regulating many of the tumor-secreted factors that stimulate tumor growth and bone destruction, such as PTHrP, IL-11, connective tissue growth factor (CTGF), the CXC chemokine receptor 4 (CXCR4), and others." (PMID 19727403, 2009). "Thus, we hypothesise that IL‐11 mainly exerts its intrinsic pro‐tumourigenic role via STAT3 activation, whereas the PI3K–AKT–mTORC1 or MAPK pathways may be triggered by IL‐11 from other cells in the tumour stroma, thus favouring tumour progression." (PMID 40673604, 2025).
tumor (continued). "Finally, we assessed whether Yap1-depletion in Yap1KD; Gp130FF tumor organoids reduced expression of gp130 cytokines and found that indeed this effect was more pronounced on IL11 than IL6." (PMID 37957015, 2024). "Thus, utilization of the gp130Y757F model of GC, in which IL-11 has a major role in GC formation, allowed for a unique opportunity to explore whether markers of tumor regression following treatment could be detected within the serum proteome." (PMID 38542101, 2024). "Moreover, IL-11 mediated bone metastasis by regulating the vicious osteolytic cycle of bone resorption and thus promoted tumor growth, implying that IL-11 may regulate osteoclast formation." (PMID 36593458, 2023). "This study has provided evidence in clinical data that IL11 high expression indicated poor prognosis in CRC, and validated using in vitro experiments in organoids and in vivo model, to establish association between IL11 pro-tumor effect and CD8+ T infiltration." (PMID 37365574, 2023). "Since gp130F/F tumour development has been shown to be driven by IL-11 upregulation, attenuated Il11 expression and tumour growth seen in the compound mutant mice suggests that IL-33 might play a key role in the persistence of inflammation that leads to tumorigenesis." (PMID 35677533, 2022). "MAFF could promote tumor invasion and metastasis through IL11 and STAT3 signaling." (PMID 36275774, 2022). "Therefore, bazedoxifene may be a potential drug for gastrointestinal cancer treatment, in which IL-11 promotes tumour development." (PMID 36615513, 2022). "Subsequently, they demonstrated elevated IL11 mRNA expression in mixed stage (stage I to IV) lung tumor tissue compared to adjacent normal tissue in a cohort of 28 patients, with the majority of patients having a tumor size ≥5 cm (71%) and nodal metastases (79%)." (PMID 35883698, 2022). "This suggests that IL-11 acting in either paracrine or autocrine fashion could lead, respectively, to cooperation or to competition between subclones, thus participating actively in the selection and evolution of tumor heterogeneity." (PMID 35096847, 2021). "However, the genetic background of the mice (C57/BL6 vs. 129/C57/BL6 mixed background) might affect the tumor cells’ dependence on IL-11 signaling." (PMID 33863879, 2021). "Importantly, IL-11+ fibroblasts appeared in the tumor tissues." (PMID 33863879, 2021). "Moreover, IL-11 is present in larger amount in cancer compared to IL-6 and, thus, it may play a relevant role in neoplastic disease." (PMID 34201209, 2021). "Immunolocalization confirmed that AN3CA tumours produce IL11 and IL11Rα protein in the human-derived tumour epitheilial cells, suggesting the potential for recombinant human IL11 to signal via IL11Rα in the tumour epitheilium and to target the receptor using our anti-human IL11Rα blocking Ab." (PMID 28186993, 2017). "Importantly, IL-11 mRNA levels were correlated with KRT8 transcript levels in tumor tissues." (PMID 29100303, 2017). "Additionally, IL-11 has the potential to promoting cancer progression in tumor microenvironment." (PMID 27028859, 2016). "Tumor metastasis comprises different processes that lead tumor cells move away from the tumor to a distant location and some authors suggested that stromal cells regulate the production of various factors implicated in metastasis process such as COX2, TNF-α, IL-6, and IL-11." (PMID 27195300, 2016). "Thus, it is possible that tumor-derived IL-11 may also promote platelet production and increase TGF-beta secretion, which may further enhance the metastatic potential of ATC cells." (PMID 27487122, 2016). "Antral tumor development in gp130757FF mice is caused by IL-11-dependent hyperactivation of STAT3, so we tested whether the cardiac stomach lesions of gp130757FF xIL-1RT1−/− mice also developed as a result of IL-11-induced STAT3 phosphorylation (pSTAT3)." (PMID 25528766, 2015). "Overall, these studies indicate that IL11 may play a role in tumour formation." (PMID 20553623, 2010).
tumor (continued). "Then, we measured the levels of IL‐11, IL‐11R, and the human NK cell marker CD56 in tumor tissues from TNBC patients." (PMID 41178513, 2026). "A cascade of pro-tumorigenic factors, including IL6, VEGFA, IL11, PDGFA, and CXCL12, further amplify the formation of complex microenvironments that support tumor cell colonization and proliferation, exacerbating the progression of CRLM." (PMID 39979806, 2025). "However, the mechanism by which IL‐11 mediates immunosuppression in tumours remains unknown." (PMID 40673604, 2025). "Downstream signalling pathways of the IL‐11/IL‐11RA axis were explored in a panel of nine LUAD cell lines and two non‐tumour cell lines." (PMID 40673604, 2025). "In pathological conditions such as cancer, colitis, and autoimmune diseases, activation of the IL11–JAK/STAT3 axis promotes inflammation, tissue remodeling, and even immunosuppression within the tumor microenvironment." (PMID 41487426, 2025). "IL11 (p = 0.010), IL23A (p = 1.77e − 05), IL27 (p = 1e − 05) and IL32 (p = 0.001) exhibited significant correlations with tumor stage." (PMID 40612864, 2025). "This signature, comprising CCL19, ICOSLG, IL11, PTGES, TNFAIP3, and TRAF3IP3, has been demonstrated to predict survival outcomes across a range of cancers and to correlate with tumor progression at the level of multi‐omics." (PMID 40714831, 2025). "In contrast, IL1A, IL11, and IL27 were downregulated, indicating their potential function as tumor suppressors." (PMID 40612864, 2025). "The expression levels of IL11, IL23A, IL27, and IL32 were significantly correlated with tumor stage." (PMID 40612864, 2025). "This study aims to unravel the involvement of IL‐11 in LUAD progression and its influence on the tumour microenvironment." (PMID 40673604, 2025). "Our data show that the IL‐11/IL‐11RA axis from tumour cells conducts the TME towards an immunosuppressive landscape and indicate that IL‐11 modulates the TME mainly by impairing T cell infiltration and by incrementing macrophage levels." (PMID 40673604, 2025). "TANs preferentially create OSM (oncostatin M), and TAMs preferentially express IL-11, which promotes STAT3 signaling in ICC cells and tumor development." (PMID 40422244, 2025). "In contrast, iCAFs reside more distally from tumor cells, promote tumor progression, and exhibit low α-SMA expression while secreting high levels of IL-6, IL-11, and other pro-tumorigenic chemokines." (PMID 41156387, 2025). "Mechanistically, VSIG1 maintains an immunosuppressive tumor environment through inhibiting the activation of CD8+ T cells and IL-11 secretion and other alternative mechanisms." (PMID 41150752, 2025). "Activated Th cells also release a variety of factors, such as IL-6, IL-11, IL-15, RANKL, and TNF-α, which promote osteoclastogenesis and bone resorption and provide a favorable environment for tumor bone metastasis." (PMID 38464516, 2024). "While YTHDF2 knockdown has been shown to inhibit HCC cell proliferation, other studies have highlighted its tumor-suppressive role by targeting genes such as EGFR, IL11, and SRPINE2." (PMID 38395751, 2024). "This inhibition of tumor metastasis, achieved by improving the gut microbiome, occurs through EMT signaling pathways, including the downregulation of IL-11 in tumors, thereby reducing cancer progression." (PMID 38732588, 2024). "For instance, RAS signaling via the AP-1 complex transcriptionally activates IL11 gene expression in cancer cells, while KRAS-mutant cells are poised to coerce cells of the tumor microenvironment into the production of cytokines." (PMID 39128004, 2024). "Tumor cells secrete several osteolytic factors, including PTH-related protein (PTHrP), IL-11, and Jagged 1, which contribute to bone degradation." (PMID 38243240, 2024).
tumor (continued). "Thus, we surmise that the effect of Yap1 inhibition may be mediated through a cancer cell–intrinsic, auto-/paracrine IL-11–dependent mechanism, which may potentially be augmented by a concomitant anti-tumor effect emanating from reduced IL-11 signalling in CD4 effector cells." (PMID 37957015, 2024). "Serum and EBC IL-11 concentrations have been reported to be increased in NSCLC patients, correlating to the severity of tumor staging." (PMID 39329890, 2024). "IL11 mutein competitively inhibit IL11 to upregulate CXCL9 and MHC-I in tumor and attenuated tumor growth." (PMID 37365574, 2023). "Immune fluorescence (IF) analysis showed that tumor infiltrating CD3+ and CD8+ cells significantly increased in Il11−/− tumors." (PMID 37365574, 2023). "IL-11 upregulates MMP-13 expression by activating PI3K, Akt, and AP-1 signaling pathways that subsequently enhances MMP-13-induced tumor metastasis." (PMID 37199584, 2023). "Interleukins can have a wide variety of pro- or anti- tumor effects and many have been therapeutically targeted in CRC clinical trials including IL-2, IL-12, IL-11, IL-6, IL-α, and IL-1β." (PMID 35205776, 2022). "IL-1, IL-6, IL-11, IL-15, IL-17, IL-23, and TNF-α are representative proinflammatory cytokines promoting tumor cell differentiation, proliferation, and survival that build up the tumor microenvironment and tumor inflammation." (PMID 36438839, 2022). "IL‐11 secreted by CAFs, due to TGF‐β exposure, triggers glycoprotein 130 (GP130)/STAT3 signaling in tumor cells, thereby demonstrating the prometastatic role of IL‐11 in CRC." (PMID 35791509, 2022). "Our genome-wide analysis using RNA- and ChIP-sequencing determined IL11 as a direct target of endogenous MAFF, which is responsible for an invasive tumor phenotype." (PMID 34262028, 2021). "Recent evidence suggests that clusters of circulating tumour cells and neutrophils accelerate haematogenous metastasis in BC66, and that neutrophils are required for IL11-induced and FIGF-induced polyclonal BC metastasis." (PMID 33674617, 2021). "Surgical procedure-induced overexpression of IL-11 promoted tumor cell growth and recurrence of HCC via activating STAT3 signaling, while blocking IL-11/STAT3 signaling dampened HCC recurrence after surgical resection." (PMID 35002979, 2021). "IL-6 and IL-11 activate STAT3 through gp130, thus establishing an IL-6, IL-11/gp130/STAT3 signaling axis that prevents enterocytes from apoptosis, and facilitates cell survival and cell proliferation, ultimately promoting tumor growth." (PMID 34440220, 2021). "YTHDF2 inhibits inflammasome-mediated tumor vascularization and malignancy by degradation of m6A-containing serpin family E member 2 (SERPINE2) and interleukin-11 (IL-11) mRNA." (PMID 33692959, 2021). "IL-11 stimulation-induced STAT3 phosphorylation in AKTP tumor organoids and human tumor cell lines, prompting us to compare the signals induced by IL-11 in normal colon and tumor organoids." (PMID 33863879, 2021). "For instance, some studies have shown that both IL6 and OSM are capable of inducing tumour-promoting effects through STAT3, while IL6, IL11, LIF and OSM can all promote invasion and metastasis through the JAK/STAT3 and PI3K/AKT pathways." (PMID 34834425, 2021). "Tumor cells directly stimulate osteoclastogenesis by expressing molecules such as RANKL, IL-6, IL-8, IL-11, IL-1, and IL-1B; they also indirectly stimulate osteoclastogenesis by increasing RANKL production in osteoblasts via PTHrP expression." (PMID 34257573, 2021). "We previously established a predictive model incorporating the tumor properties of vascular invasion and TNM stage, and CXCR4, CTGF, and IL-11 proteins to predict bone metastasis in HCC." (PMID 33588789, 2021). "Expression of phospho-STAT3 and MECA32 staining was also examined from primary tumor tissues to examine the effect of MAFF and IL11 on STAT3 pathways and microvessel density." (PMID 34262028, 2021).